ERCC1 (ERCC excision repair 1, endonuclease non-catalytic subunit)
Diseases named in the same sentence as ERCC1 in open-access papers (continued):
Sharing a sentence is not in itself a finding about the gene and the disease.
cancer (continued). "In addition, genetic studies identified an association between late radiation-induced fibrosis and polymorphisms in the ATM, TGFB, ERCC1, and ERCC5 genes for cancer patients who had been treated with radiotherapy." (PMID 32775415, 2020). "The value of ERCC1 has also been confirmed in other cancers." (PMID 32397531, 2020). "The difference concerning the expression of ERCC1 in several cancers may be due to the different types of cancer and/or the different roles of ERCC1 in these various tumors." (PMID 33029487, 2020). "We also found BBR decreased the levels of ERCC1, as ERCC1 is a vital factor in NER to repair the DNA damage caused by cisplatin, BBR may function in interfering with NER to sensitize cancer cells to chemotherapeutic drugs." (PMID 31338966, 2019). "Therefore, the correlation between ERCC1 level and the resistance to cancer treatments makes this complex a potential biomarker for the prediction of patient survival in several cancer types." (PMID 30563071, 2018). "The importance of this result must be related with ERCC1 which is overexpressed in cancer cells." (PMID 30386247, 2018). "Together these data support a novel target of EGCG in cancer cells, namely ERCC1/XPF." (PMID 30400270, 2018). "Based on data from studies in other cancers, certain biomarkers could be potentially associated with platinum resistance in EPNEC and SCLC such as ERCC1 (Excision repair cross-complementation group 1), Lin28a, Bcl-2 (B-cell lymphoma 2) and Ki-67." (PMID 28955403, 2017). "We found that BRCA1 and ERCC1 proteins were located in the nuclei of cancer cells." (PMID 28404895, 2017). "Our findings suggest that an abnormality in the promoter region might enhance ERCC1 protein expression in C. albicans-induced cancer." (PMID 27410681, 2016). "Higher mRNA levels of ERCC1 are associated with lack of platinum response in advanced lung, ovarian, bladder, and gastrointestinal cancers." (PMID 25253066, 2014). "However, correlation between genotypes of ERCC1 gene and the expression of ERCC1 protein in cancer cells is still controversial." (PMID 25028118, 2014). "Overexpression of two key genes involved in the early steps of the NER process, ERCC1 and XPC, is associated with liver fibrogenesis and cancer and could be related to the well-recognized resistance of HCC to chemotherapeutics." (PMID 24877058, 2014). "A previous study has shown that overexpression of two NER genes, ERCC1 and XPC, is associated with liver fibrogenesis and cancer and could be related to the well-recognized resistance of HCC to chemotherapeutics." (PMID 24877058, 2014). "A nucleotide excision repair (NER) protein known as the excision repair cross-complementing group 1 (ERCC1) may serve as a useful predictor for treatment response to cancer therapies." (PMID 25191856, 2014). "Further, klotho could modulate the repair activity of the DNA through regulation of ERCC1, then change the resistance of the cancer cells." (PMID 23437382, 2013). "An enhanced expression of CSC markers in the residual cancer cells after chemotherapy treatments coincided with an enhanced expression of ERCC1 and/or β-tubulin isotype III, the two proteins commonly associated with resistance of cancer cells to platinum and taxane-based chemotherapies." (PMID 23537295, 2013). "Furthermore, high levels of ERCC-1 protein support the efficient DNA repair capacity of resistant cancer cells and ERCC-1 is a marker gene for the NER mechanism." (PMID 23817665, 2013). "Expression of the ERCC1 protein was detected in the nuclei of cancer cells." (PMID 23940741, 2013). "The excision repair cross-complementing rodent repair deficiency complementation group 1 (ERCC1) gene is reported to be a crucial gene in the NER pathway, and ERCC1 polymorphisms can modify the function of NER and, thus, influence the risk of human cancers." (PMID 23385236, 2013).
cancer (continued). "ERCC1 has also been supported by studies that demonstrate cancers with extensive genomic alterations have more malignant phenotype and increased growth rates, and ERCC1 may be representative of the intrinsic DNA damage-repair ability of the cell." (PMID 22616552, 2012). "Several preclinical and clinical studies have investigated the expression of ERCC1 mRNA and protein in multiple cancer types and have demonstrated a correlation between the ERCC1 expression levels and the treatment response to platinum-based therapy and/or survival outcome." (PMID 23259415, 2012). "This could indicate selection of sub-clones for which epigenetically reduced expression of Pms2, Ercc1 and/or Xpf was reversed under the new micro-environment of a growing cancer." (PMID 22494821, 2012). "Furthermore, the enforced increase of miR-138 levels in the A549/DDP cells down-regulates expression of ERCC1 and increases sensitivity of the drug-resistant cancer cells to cisplatin by inducing apoptosis." (PMID 22954303, 2012). "However, since ERCC1 is also involved in the repair of cisplatin-induced DNA adducts in cancer cells, high expression levels increase resistance to platinum-based chemotherapies, while low expression leads to drug sensitivity." (PMID 22629454, 2012). "Altogether the clinical studies together with in vitro data suggest that ERCC1 may serve as a reliable predictive marker for resistance to cisplatin in human cancers." (PMID 20846399, 2010). "Our study suggests that targeting ERCC1-XPF might be a strategy for improving the therapeutic efficacy of cisplatin for other types of cancer." (PMID 20846399, 2010). "While there are indications that the relative ERCC1 mRNA level is a good marker for NER activity in human cancer cells, it is unclear whether expression of this gene has any relationship to other pathways of DNA repair." (PMID 22276017, 2009). "Globally, it also suggests the possibility that ERCC1 might have alternative functions in cancer cells." (PMID 19578506, 2008). "Future trials will need to be pharmacogenomic based and integrate the best biomarkers if personalised cancer therapy is to become a reality and to explore how cisplatin resistance might be reversed by ERCC1 target modulation." (PMID 22275966, 2008). "Previous studies have shown that downregulation of key NER proteins, such as ERCC1, can increase the sensitivity of cancer cells to chemotherapeutic agents, including CDDP and mitomycin C, suggesting that targeting NER components could improve chemotherapy efficacy." (PMID 40076972, 2025). "Therefore, the outcome of cancer therapy could be influenced by chemotherapeutic agents controlling ERCC1 protein stability such as Bortezomib." (PMID 38272916, 2024). "Therefore, ERCC1 expression should be studied in patients with other HER2 overexpressing cancers." (PMID 36338712, 2022). "Conversely, the inhibition of ERCC1 may sensitize cancer cells to cisplatin." (PMID 36713431, 2022). "Also, the isoform switches are highly predictive for cancer survival and aggressiveness, such as the DNA excision repair 1 (ERCC1) gene resulting in a protein lacking the HHH domain associated with lower cancer survival rates." (PMID 33761087, 2021). "Together with xeroderma pigmentosum complementation group F (XPF), ERCC1 forms a heterodimer complex and participates in the elimination of different DNA adducts induced by UV light, reactive oxygen species, environmental mutagens, and especially cancer chemotherapy drugs during NER." (PMID 35056973, 2021). "Therefore, the levels of ERCC1 were significantly lower in cancer patients than in normal controls." (PMID 34350111, 2021). "In TGCT cancer cell lines it has been reported an association of the cisplatin non-sensitivity with high levels of ERCC1, suggesting that this marker could be a potential mediator of response to cisplatin and a prognostic factor." (PMID 32167697, 2020).
cancer (continued). "Notably, the increase of ERCC1 expression or of ATP7B and the loss of CTR1 have been all consistently reported as mechanisms of platinum resistance as well as predictors of poor response to platinum-based chemotherapy in cancer patients, including HNSCC." (PMID 33015030, 2020). "In contrast, 45% of CRC patients without cancer-associated variants had ERCC1 variant (P = 0.04)." (PMID 30850667, 2019). "ERCC1 protein is involved in nucleotide excision repair of damaged DNA and determination of ERCC1 mRNA expression may be clinically useful for cancer treatment, as one of the mechanisms of resistance to platinum chemotherapy drugs has been shown to be correlated with high ERCC1 activity." (PMID 27387303, 2016). "ERCC1 protein is involved in nucleotide excision repair of damaged DNA and determination of ERCC1 mRNA expression may have be clinically useful for cancer treatment, because one of the mechanisms of resistance to platinum chemotherapy drugs is correlated with high ERCC1 activity." (PMID 26031756, 2015). "Cancer cells with low expression of ERCC1 have a decreased ability to repair DNA damage, an increase in the number of EGFR mutations and increased sensitivity to platinum-based chemotherapy, which may be why patients with NSCLC with EGFR mutations have a higher response rate to chemotherapy." (PMID 25667646, 2015). "The mRNA expression levels of ERCC1 and TS may vary with different stage of cancer." (PMID 25175730, 2014). "Therefore, potentially functional ERCC1 and ERCC2 SNPs may affect cellular DNA repair capacity and thus may be associated with various survival rates observed in cancer patients." (PMID 24023723, 2013). "Therefore, it is possible that, in some tissues progressing to cancer, one or more of these proteins that interact with Ercc1 and/or Xpf may provide both stability and nuclear transport for one member of the pair when the other is reduced or absent." (PMID 22494821, 2012). "Thus, it appears that a field defect comprising about 1 million crypts, with most crypts expressing reduced protein levels of Pms2 and Ercc1, but high levels of Ku86, surrounds the cancers of these patients, and likely similar field defects surround TVAs as well." (PMID 22494821, 2012). "Investigations into DNA repair proteins have identified the Excision Repair Cross Complementation Group 1 (ERCC1) and Xeroderma Pigmentosum Complementation Group F (XPF) complex as being more highly expressed in cancer cell lines that exhibit chemoresistance." (PMID 39051064, 2024). "Initially, we conducted an examination of mRNA expression levels of seven ERCC genes (ERCC1-6 and ERCC8) in various cancer tissues." (PMID 39192988, 2024). "Most notably, racial differences between Black and White samples in the expression of genes pertaining to homology-directed repair, including RAD50, RAD51, MRE11, ERCC1, and BRCA2, were observed in five cancer types." (PMID 37345032, 2023). "There were no significant changes in gene expression levels for the seven other cancer genes (ABCC1, ALK1, BRCA1, DHRS2/HEP27, EGFR, ERBB2, and ERCC1)." (PMID 35743133, 2022). "In the process of single-stranded DNA repair, ERCC1-XPF cuts the damaged strand 5′ to remove the damaged base, creating 3′-OH in order to prime DNA synthesis to complete DNA repair and reduce cancer cell apoptosis." (PMID 36230725, 2022). "Cancer can become resistant to, for example, cisplatin by overexpressing both XPF and ERCC1 proteins." (PMID 33297561, 2020). "Patients with an ERCC1-positive expression had a significantly better five-year disease-free survival (DFS) than those with an ERCC1-negative expression, 62% to 49%, and cancer-specific survival (CSS), 70% to 59%, respectively." (PMID 32397531, 2020). "In previous studies, we have downregulated ERCC1-XPF at ~90–95% levels and shown that this highly sensitizes cisplatin treated cancer cells." (PMID 30279363, 2018).
cancer (continued). "Of those, we highlight four genes related to cancer development and progression (NOTCH2, ERBB2, MST1R, and RAF1) and two DNA repair genes (ERCC1 and SLX4)." (PMID 29868112, 2018). "As a key endonuclease in a major DNA repair pathway, the role of ERCC1-XPF in the development of ageing, neurodegenerative disease and especially in multiple forms of cancer has been widely investigated." (PMID 28903417, 2017). "While the evidence supporting the chemosensitizing effect of ERCC1 underexpression in response to platinum agents was somewhat consistent across all retrospective studies in NSCLC, the evidence for other cancer types was often inconclusive or contradictory." (PMID 27888622, 2017). "Switching on and off of an array of genes such as BRCA1, BRCA2, Akt1, ERCC1 and ABCB1 were identified to modulate sensitivity toward chemotherapy in cancer patients." (PMID 27980217, 2017). "More recently small molecules have been identified that target the protein-protein interaction domain of ERCC1-XPF and increase toxicity of alkylating agents in cancer cells." (PMID 27650543, 2016). "ABCG2 and ERCC1 can both serve as chemoresistance markers for most types of cancer, and in the present study, we measured the IC50 values of DDP and the expression levels of ABCG2/ERCC1 to investigate DDP resistance in TSCC cells." (PMID 26517090, 2015). "Finally, the accumulated evidence provided by a meta-analysis of the literature clearly indicated that ERCC1 T19007C and C8092A polymorphisms might not act as risk factors for cancer." (PMID 25253066, 2014). "Increasing evidence has demonstrated that the expression levels of ERCC1, TYMS, TUBB3, RRM1 and TOP2A are closely correlated with the pathogenesis of carcinomas." (PMID 24926347, 2014). "ERCC1 is one of the key factors in the NER system, and the expression of this endonuclease was identified as a prognostic marker in several types of cancer, including HNSCC." (PMID 23613873, 2013). "A previous study has proved that the suppression of ERCC1 expression in human cancer cells leads to an increased sensitivity to CDDP, and ERCC1 has been presumed to be an attractive target to confer increased cellular sensitivity to CDDP-based chemotherapy." (PMID 20470393, 2010). "Changes in ERCC1, ERCC2, XRCC1, and XRCC3 may potentially influence cancer development by disturbing the DNA repair mechanism." (PMID 39834980, 2024). "The modulation of ERCC1 in DDR and the possibility that it represents a decision point between cell survival and apoptosis can have critical impact in chemotherapy response in cancer patients." (PMID 38272916, 2024). "USP45 complexed with Spindly promotes cancer cell migration, and as a critical regulator in DNA damage repair via deubiquitinating ERCC1 it, in turn, stabilizes the XPF–ERCC1 complex promoting survival of cancer cells exposed to the DNA damage agents in cancer treatments." (PMID 36765885, 2023). "Emerging evidence associates the expression levels of genes involved in the NER process and some types of cancer, while data on STS are limited, so we evaluated the gene expression of three key genes (ERCC1, ERCC2 and ERCC5) in the NER pathway in 24 tissue samples from the 32 patients in our cohort." (PMID 35955506, 2022). "Researchers have suggested that the HER2 status may influence the effect of TOP2A on inhibitors on cancer cells, and a significant correlation exists between the expression of RRM1 and ERCC1 and response to chemotherapy." (PMID 35711974, 2022). "The ERCC1-XPF heterodimer is a key endonuclease in numerous single and double strand break repair processes, and inhibition of the heterodimerization has previously been shown to sensitize cancer cells to DNA damage." (PMID 35372043, 2022). "The same relationship was observed between ERCC1-negative tumors and cancer-specific survival (p = 0.032)." (PMID 33266377, 2020).
cancer (continued). "In upper tract urothelial carcinoma, however, ERCC1 expression was not predictive of overall survival (p = 0.48) or cancer-specific survival (p = 0.33) in patients that underwent radical nephroureterectomy." (PMID 33266377, 2020). "Hypersensitivity of ERCC1 and XPF mutant cells to crosslinking anti‐cancer drugs is well documented; however, whether SNM1A‐deficient cells recapitulate this sensitivity is unknown." (PMID 31273933, 2019). "Additionally, it is known that resistances to platinum-based therapy correlate with high expression of ERCC1 and can be reversed by blocking the interaction between ERCC1 and XPA, which is essential for NER, sensitizing cancer cells to NER substrates." (PMID 29416673, 2018). "In addition, an integrated haplotype analysis of 5 SNPs in ERCC1, CD3EAP, and PPP1R13L on 19q13 was performed to explore higher LD with the cancer‐related SNP." (PMID 30453383, 2018). "In this work, we identified another target of EGCG, ERCC1/XPF, which has important implications for understanding the mechanism of the EGCG-mediated sensitization of tumors to cisplatin and for improving current cancer treatment strategies." (PMID 30400270, 2018). "There was no treatment-related death both in ERCC1+ and ERCC1- population, but ten cancer-related deaths (33%) occurred in ERCC1+ cohort." (PMID 27147577, 2016). "Nephrotoxicity has been related to the C allele in rs3212986 ERCC1, T allele in rs11615 ERCC1 and C/T genotype in rs3212986 ERCC1, independent of cancer type." (PMID 25452763, 2014). "We therefore suggest that future explorative studies of ERCC1 copy number alterations in other cancer types also investigate ERCC4 copy numbers, as these may potentially play a role in ERCC1 expression." (PMID 24144331, 2013). "More recent results modified these observations, since knockdown of Xpf mRNA expression by siRNA (and consequent loss of Xpf protein expression) did not eliminate protein expression of Ercc1 in a human cancer cell line." (PMID 22494821, 2012). "We studied 39 consecutive NSCLC patients and measured the expression of six molecular markers (MDR-1, LRP, RRM-1, EGFR, ERCC-1, BRCA-1) in their primary tumors and metastatic lymph nodes and four well-known serum markers for cancer (NSE, CEA, CA-125, CYFRA 21-1)." (PMID 22890830, 2012). "Curcumin also inhibits DNA repair pathways in cancer cells, like the fanconi anemia/BRCA (FA/BRCA) pathway, or downregulates DNA repair proteins MGMT (O6-methylguanine-DNA methyltransferase), DNAPK, Ku70, Ku80, and ERCC-1." (PMID 22247744, 2011). "The expression levels of TS, TP, and ERCC1, as determined by IHC, in cancer tissue were not significantly different in relapsed and non-relapsed patients." (PMID 19259093, 2009). "Although above studies suggested that both ERCC1 and BRCA1 may serve as effective biomarkers for chemosensitivity in cancer patients with primary tumor, the information on these biomarkers is still limited in metastases." (PMID 18402708, 2008). "In the New Hampshire population, we found no differencein ERCC1 expression level according to cancer status (p = 0.8)." (PMID 16882524, 2006). "Furthermore, the use of RNA interference as a means of inhibiting the ERCC1-XPF complex is an attractive approach and was confirmed in multiple studies to demonstrate effectiveness in increasing cisplatin efficacy within multiple cancer cell lines." (PMID 32344513, 2020). "Five genes are involved in DNA repair, a role closely related to genome maintenance and cancer, and were shown to have a protective role in various types of cancer (only one paper is cited by gene, but many others confirm this role): EXO1, ERCC1, GTF2H1, MDC1, and DGCR8." (PMID 31568528, 2019).